ZNF888 (zinc finger protein 888)
Description:
May be involved in transcriptional regulation.
Tractability: PROTAC: UniProt records ubiquitination sites on it; ubiquitination databases record sites on it.
Gene: Protein-coding gene on chromosome 19 (52,904,415 to 52,923,496, reverse strand). Ensembl gene ENSG00000213793.
Subcellular location: Nucleus
Gene Ontology:
Molecular function: DNA-binding transcription factor activity, RNA polymerase II-specific; RNA polymerase II cis-regulatory region sequence-specific DNA binding
Biological process: regulation of transcription by RNA polymerase II; regulation of DNA-templated transcription
Cellular component: nucleus
Genetic constraint (gnomAD): Loss-of-function variants: 5 observed, 5.95 expected, observed/expected ratio (o/e) 0.84, 90% interval 0.44 to 1.66. That is too few expected variants to judge how well the gene tolerates losing a copy. Missense variants: 716 observed, 875.81 expected, observed/expected ratio (o/e) 0.82, 90% interval 0.77 to 0.87. Synonymous variants: 240 observed, 280.86 expected, observed/expected ratio (o/e) 0.85, 90% interval 0.77 to 0.95.
Homologues: Orthologues: chimpanzee ZNF888 (98% identical). Paralogues in human: ZNF813 (63% identical), ZNF761 (60% identical), ZNF860 (57% identical), ZNF816 (56% identical), ZNF578 (56% identical), ZNF468 (54% identical), ZNF701 (53% identical), ZNF765 (51% identical), ZNF525 (48% identical), ZNF766 (36% identical).
Diseases named in the same sentence as ZNF888 in open-access papers:
ZNF888 is named in the same sentence as 3 diseases in open-access papers, as found by Europe PMC text mining. Sharing a sentence is not in itself a finding about the gene and the disease. The quoted sentences say what the papers report.
clear-cell renal cell carcinoma (1 paper, 2025). "Particularly, among the forecasted top 20 TFs, ZNF888 has been pinpointed as a methylation-influenced gene correlated with clear-cell renal cell carcinoma." (PMID 40729372, 2025).
cancer (1 paper, 2025). A tumor composed of atypical neoplastic, often pleomorphic cells that invade other tissues. "The probability of these six genes to be mutated in normal tissue adjacent to cancer is CPA6 (3.85%), ZNF888 (46.15%), SH3BP1 (76.92%), ANKRD16 (30.77%), ATN1 (11.54%), and C4orf54 (80.77%)." (PMID 40688112, 2025).
tumor (1 paper, 2025). "Comparing the expression of SH3BP1, CPA6, ZNF888, and NKRD16 in COAD and READ tumor and normal tissues revealed that SH3BP1 expression increased in COAD and READ and was more prevalent in tumor tissues than in the other susceptibility genes obtained by whole-genome sequencing." (PMID 40688112, 2025).